SLC13A2 (solute carrier family 13 member 2)
Description:
Low-affinity sodium-dicarboxylate cotransporter, that mediates the entry of citric acid cycle intermediates, such as succinate, citrate, fumarate and alpha-ketoglutarate (2-oxoglutarate) into the small intestine and renal proximal tubule. Transports the dicarboxylate into the cell with a probable stoichiometry of 3 Na(+) for 1 divalent dicarboxylate, rendering the process electrogenic. Citrate is transported in protonated form as a divalent anion, rather than the trivalent form which is normally found in blood. Has a critical role in renal dicarboxylate transport (By similarity).
Synonyms: NaDC-1; NADC1; SDCT1; NaCT
Tractability: Small molecule: a structure with a bound ligand is known. Antibody: UniProt places it where antibodies can reach, with high confidence; its Gene Ontology location is reachable by antibodies, with high confidence; UniProt predicts a signal peptide or a membrane-spanning region. PROTAC: a small molecule that binds it is known.
Target class: SLC13 family of sodium-dependent sulphate/carboxylate transporters; Electrochemical transporter; SLC superfamily of solute carriers; Transporter
Gene: Protein-coding gene on chromosome 17 (28,473,275 to 28,497,782, forward strand). Ensembl gene ENSG00000007216.
Subcellular location: Apical cell membrane
Pathways (Reactome):
Transport of small molecules: SLC-mediated transport of organic anions
Gene Ontology:
Molecular function: alpha-ketoglutarate transmembrane transporter activity; citrate transmembrane transporter activity; fumarate transmembrane transporter activity; protein binding; sodium:dicarboxylate symporter activity; succinate transmembrane transporter activity; low-affinity sodium:dicarboxylate symporter activity; solute:sodium symporter activity; transmembrane transporter activity
Biological process: alpha-ketoglutarate transport; cellular response to lithium ion; fumarate transport; succinate transmembrane transport; intestinal absorption; transmembrane transport; citrate transport; sodium ion transmembrane transport
Cellular component: apical plasma membrane; extracellular exosome; membrane; plasma membrane
Genetic constraint (gnomAD): Loss-of-function variants: 40 observed, 60.52 expected, observed/expected ratio (o/e) 0.66, 90% interval 0.51 to 0.86. The upper end of that interval is the gene's LOEUF score, 0.86, which puts it in group 3 of 6, group 1 being the genes least tolerant of losing a copy. Missense variants: 694 observed, 808.19 expected, observed/expected ratio (o/e) 0.86, 90% interval 0.81 to 0.91. Synonymous variants: 341 observed, 344.93 expected, observed/expected ratio (o/e) 0.99, 90% interval 0.9 to 1.08.
Homologues: Orthologues: chimpanzee SLC13A2 (99% identical), macaque SLC13A2 (93% identical), dog SLC13A2 (81% identical), rabbit SLC13A2 (77% identical), pig SLC13A2 (77% identical), mouse Slc13a2 (76% identical), rat Slc13a2 (76% identical), guinea pig SLC13A2 (74% identical), tropical clawed frog slc13a2 (62% identical), zebrafish slc13a2 (58% identical), Caenorhabditis elegans nac-1 (38% identical), Caenorhabditis elegans nac-3 (37% identical), and 6 more. Paralogues in human: SLC13A5 (52% identical), SLC13A1 (45% identical), SLC13A3 (44% identical), SLC13A4 (41% identical), OCA2 (21% identical).
Diseases named in the same sentence as SLC13A2 in open-access papers:
SLC13A2 is named in the same sentence as 19 diseases in open-access papers, as found by Europe PMC text mining. Sharing a sentence is not in itself a finding about the gene and the disease. The quoted sentences say what the papers report.
kidney stones (9 papers, 2013 to 2025). "The aim of this study is to determine the frequency of the rs11568476 polymorphism in the SLC13A2 gene among Turkish patients with calcium-containing kidney stones and to assess its association with hypocitraturia." (PMID 40868238, 2025). "This study aimed to investigate the presence of the rs11568476 polymorphism in SLC13A2 and its association with hypocitraturia in Turkish patients with calcium-containing kidney stones." (PMID 40868238, 2025). "This study investigated the presence of the rs11568476 (V477M) polymorphism in the SLC13A2 gene in Turkish patients with calcium-containing nephrolithiasis, particularly focusing on its relationship with hypocitraturia, a known and common metabolic risk factor for kidney stone formation." (PMID 40868238, 2025). "The main function of SLC13A2 is renal handling of citrate and therefore important in the formation of kidney stones and nephrolithiasis." (PMID 24688728, 2013). "In contrast, PF-06761281 showed significant activity on the closely related transporters NaDC1 (gene symbol SLC13A2) and NaDC3 (gene symbol SLC13A3), leading to increased urinary calcium excretion, which may have unfavourable effects on bone health and kidney stone formation." (PMID 36005604, 2022).
Hepatic fibrosis (1 paper, 2025). The presence of excessive fibrous connective tissue in the liver. "More intriguingly, sirius red staining revealed increased collagen fibers in the mouse liver with SLC13A2 deficiency, indicating suppressed regenerative capacity resulted in hepatocyte injury and hepatic fibrosis, especially under chronic damaging conditions." (PMID 39824985, 2025).
liver cancer (1 paper, 2025). An epithelial or non-epithelial malignant neoplasm that arises from the liver. "Even more interestingly, SLC13A2 exhibits equally beneficial effects in both scenarios by facilitating liver regeneration and ameliorating liver cancer progression." (PMID 39824985, 2025).
mastocytoma (1 paper, 2019). A localized tumor composed of sheets of mast cells without atypia. "SLC13A2 was down regulated along with miR-9 overexpression in malignant murine mastocytoma cell lines, and in primary canine osteosarcoma (OSA) tumors and cell lines." (PMID 30991985, 2019).
cancer (3 papers, 2017 to 2022). A tumor composed of atypical neoplastic, often pleomorphic cells that invade other tissues. "SLC13A2 and SLC13A5 are also upregulated supporting an enhanced import of citrate into cancer cells in cluster 2 tumors." (PMID 36119118, 2022).
tumor (3 papers, 2019 to 2025). "In another parallel study from our group, we also found that SLC13A2-transported citrate releases acetyl-CoA to suppress tumor growth through the acetylation and degradation of a key glycolytic enzyme pyruvate kinase muscle isozyme M2 (PKM2)." (PMID 39824985, 2025). "We also found a significant corresponding increase in expression in the differentiation marker, SLC13A2, and altered Kras splicing in these tumours." (PMID 35589755, 2022).
SLC13A2 also shares sentences with these, for which no sentence is quoted: Hyperoxaluria (2 papers); asthenozoospermia (1); Calcium nephrolithiasis (1); calcium oxalate kidney stones (1); cervical cancer (1); Hypercalciuria (1); lung carcinoma (1); lymph node metastasis (1); Obesity (1); osteosarcoma (1); prostate carcinoma (1); renal carcinoma (1); thyroid cancer (1).